TMPRSS6 (transmembrane serine protease 6)
Description:
Membrane-bound serine protease. Through the cleavage of cell surface hemojuvelin (HJV), a regulator of the expression of the iron absorption-regulating hormone hepicidin/HAMP, plays a role in iron homeostasis.
Synonyms: FLJ30744; MT2; IRIDA
Tractability: Small molecule: a high-quality ligand is known. Antibody: UniProt places it where antibodies can reach, with high confidence; its Gene Ontology location is reachable by antibodies, with high confidence; UniProt predicts a signal peptide or a membrane-spanning region. PROTAC: its protein half-life has been measured; a small molecule that binds it is known.
Target class: Enzyme; Protease; Serine protease
Gene: Protein-coding gene on chromosome 22 (37,065,005 to 37,110,890, reverse strand). Ensembl gene ENSG00000187045.
Subcellular location: Cell membrane
Pathways (Reactome):
Extracellular matrix organization: Collagen degradation; Degradation of the extracellular matrix
Gene Ontology:
Molecular function: protein binding; metalloendopeptidase activity; serine-type peptidase activity; serine-type endopeptidase activity
Biological process: membrane protein proteolysis; multicellular organismal-level iron ion homeostasis; negative regulation of DNA-templated transcription; self proteolysis; collagen catabolic process; extracellular matrix disassembly; intracellular iron ion homeostasis; negative regulation of transcription by RNA polymerase II; positive regulation of transcription by RNA polymerase II; protein processing; proteolysis
Cellular component: extracellular region; plasma membrane
Genetic constraint (gnomAD): Loss-of-function variants: 62 observed, 93.27 expected, observed/expected ratio (o/e) 0.66, 90% interval 0.54 to 0.82. The upper end of that interval is the gene's LOEUF score, 0.82, which puts it in group 3 of 6, group 1 being the genes least tolerant of losing a copy. Missense variants: 1,026 observed, 1,075 expected, observed/expected ratio (o/e) 0.95, 90% interval 0.91 to 1. Synonymous variants: 452 observed, 462.28 expected, observed/expected ratio (o/e) 0.98, 90% interval 0.9 to 1.06.
Gene-disease validity (ClinGen):
ClinGen rates the evidence that TMPRSS6 causes each of these diseases.
IRIDA syndrome (autosomal recessive): Definitive. IRIDA (Iron-refractory iron deficiency anemia) syndrome is a rare autosomal recessive iron metabolism disorder characterized by iron deficiency anemia (hypochromic, microcytic) that is often unresponsive to oral iron intake and partially responsive to parenteral iron treatment.
Homologues: Orthologues: chimpanzee TMPRSS6 (99% identical), dog TMPRSS6 (93% identical), pig TMPRSS6 (91% identical), macaque TMPRSS6 (91% identical), rat Tmprss6 (84% identical), mouse Tmprss6 (84% identical), guinea pig TMPRSS6 (76% identical), tropical clawed frog tmprss6 (54% identical), Drosophila melanogaster Sb (17% identical), Drosophila melanogaster CG17242 (7% identical). Paralogues in human: ST14 (30% identical), TMPRSS7 (26% identical), TMPRSS15 (22% identical), TMPRSS9 (19% identical), TMPRSS13 (19% identical), TMPRSS3 (18% identical), TMPRSS2 (17% identical), TMPRSS5 (17% identical), HPN (16% identical), TMPRSS11E (16% identical), TMPRSS11A (15% identical), TMPRSS11B (15% identical), and 5 more.
Diseases named in the same sentence as TMPRSS6 in open-access papers:
TMPRSS6 is named in the same sentence as 73 diseases in open-access papers, as found by Europe PMC text mining. Sharing a sentence is not in itself a finding about the gene and the disease. The quoted sentences say what the papers report.
iron deficiency (67 papers, 2012 to 2026). "Human genetics clearly support the development of modulators of this pathway, as patients with loss-of-function mutations in TMPRSS6 show high hepcidin levels and have iron-refractory iron-deficient anemia." (PMID 40548380, 2025). "The most common SNP in the TMPRSS6 gene that is strongly associated with iron deficiency anemia is rs855791." (PMID 41159619, 2025). "HFE (rescaled by TSAT) and TMPRSS6 (iron) were strongly associated with inverse risk of iron-deficiency anaemia." (PMID 39643614, 2024). "The final SNP in TMPRSS6 examined in this review, rs2413450, was associated with iron deficiency markers in two studies." (PMID 39599580, 2024). "WES (whole exome sequencing) testing identifies iron-refractory iron deficiency anemia caused by a mutation in the TMPRSS6 gene." (PMID 39354993, 2024). "Studies in Tmprss6−/− mice revealed that increases in dietary iron to ∼0.5% were sufficient to overcome the high hepcidin barrier and to correct iron-deficiency anemia." (PMID 37690687, 2023). "Hepcidin transcription is suppressed by iron deficiency, partly via matriptase-2 (encoded by TMPRSS6) mediated downregulation of hemojuvelin, a coreceptor for BMP signaling." (PMID 36928379, 2023). "Earlier studies show that the heterozygous Tmprss6+/− mice retain the ability to reduce hepcidin expression similar to the wild-type Tmprss6+/+ counterparts but they are more prone to iron deficiency when iron demands are high." (PMID 37690687, 2023). "Hepsin is associated with some diseases, especially cancer, while TMPRSS6 is mainly involved in iron metabolism and iron deficiency anemia." (PMID 37888440, 2023). "Combined ablation of Tmprss6 and Hfe or Tfr2 genes shows a phenotype similar to the Tmprss6−/− mice with an inappropriately high hepcidin expression and iron deficiency anemia." (PMID 37690687, 2023). "Results indicate that the expression of ∼22% Tmprss6 mRNA of wild-type mice in Tmprss6−/− mice was unable to correct the high hepcidin expression and iron deficiency status." (PMID 37690687, 2023). "Iron-refractory iron deficiency anaemia (IRIDA) is an autosomal recessive iron deficiency anaemia caused by mutations in the TMPRSS6 gene." (PMID 36604716, 2023). "TMPRSS6 is expressed in the liver and plays an essential role in regulating the expression of the main regulator of iron homeostasis hepcidin; mutations in Tmprss6 induce high hepcidin levels, which cause iron-refractory iron deficiency anemia." (PMID 35547804, 2022). "This is supported by findings in TMPRSS6 haploinsufficient mice that are more susceptible to developing iron deficiency under the condition of iron restriction or an increased iron requirement." (PMID 35893046, 2022). "TMPRSS6 polymorphisms are associated with the risk of developing iron deficiency anemia (IDA) in individuals of European and Asian ancestry." (PMID 36295822, 2022). "IRIDA is one type of iron-deficiency anemia due to mutation of the transmembrane serine protease 6, which cleaves HJV and, in turn, inhibits BMP-6-induced hepcidin expression." (PMID 34679725, 2021). "Adult Tmprss6−/− mice were shown to excessively express the Hamp gene, leading to hypochromic, microcytic iron-deficiency anemia)." (PMID 34573364, 2021). "Under hypoxia and iron deficiency, the expression of transmembrane serine protease 6 (TMPRSS6 or matriptase-2), which cleaves membrane-bound HJV, is increased leading to hepcidin suppression." (PMID 33987030, 2021). "Genotypes and allele frequencies of TMPRSS6 (rs1421312) polymorphism in normal subjects and in iron deficiency anemia group." (PMID 34780475, 2021). "TMPRSS6 has an essential role in iron homeostasis and has been linked to iron-refractory iron deficiency anaemia." (PMID 35178045, 2021). "Variants at DUOX2, F5, SLC11A2 and TMPRSS6 associate with iron deficiency anemia, while variants at TF, HFE, TFR2 and TMPRSS6 associate with iron overload." (PMID 33536631, 2021).
iron deficiency (continued). "TMPRSS6 rs855791 is associated with iron deficiency anaemia and IRIDA, with elevated hepcidin, reduced iron and reduced haemoglobin indices." (PMID 32609760, 2020). "TMPRSS6 function is essential in iron deficiency to allow the compensatory mechanism of increased iron absorption." (PMID 31649559, 2019). "A spectrum of conditions can be envisaged ranging from classic severe IRIDA due to homozygous or compound heterozygous TMPRSS6 mutations to increased susceptibility to iron deficiency conferred by single mutations/polymorphic changes." (PMID 31649559, 2019). "Further, we treated Tmprss6−/−mice with iron in order to determine the specific contribution of iron deficiency in the development of obesity within the same mouse model." (PMID 29636509, 2018). "Gross epithelial manifestations of iron deficiency or depletion such as glossitis or cheilosis or common alleles of the TMPRSS6 gene that encodes matriptase-2, a serine protease that represses hepcidin, probably do not cause or influence pica." (PMID 26880930, 2016). "Analysis of samples from iron-deficient animals confirmed the previously reported increase of TMPRSS6 protein by iron deficiency." (PMID 26845567, 2016). "Since it is very well known that mouse liver hepcidin (Hamp) mRNA content sensitively reacts to iron deficiency, iron overload or the rate of erythropoiesis, it is essential to know how TMPRSS6 protein content changes in response to these stimuli." (PMID 26845567, 2016). "The aim of this study was to determine TMPRSS6 protein content in experimental animals subjected to iron deficiency, iron overload or erythropoietin (EPO) administration." (PMID 26845567, 2016). "IRIDA is caused by mutations in TMPRSS6, the gene encoding matriptase-2, which downregulates hepcidin expression under conditions of iron deficiency." (PMID 25805669, 2015). "Spleen iron of Tmprss6 KO mice is comparable with that of wild type littermates, thus inappropriate for its condition of iron deficiency." (PMID 25860887, 2015). "Supporting these observations, TMPRSS6-haploinsufficient mice were found to be more susceptible to iron deficiency under conditions of iron restriction or an increased iron requirement, such as pregnancy." (PMID 25805669, 2015). "Another recent study evaluated the predisposition to IDA in the Chinese population and found 2 TMPRSS6 polymorphisms (rs855791 and rs4820268) to be genetic risk factors for iron deficiency and IDA." (PMID 25805669, 2015). "Tfr2 function becomes more evident in iron deficiency, as exemplified by Tmprss6-/-Tfr2-/- double knock out mice." (PMID 24847265, 2014). "Matriptase-2 was later established to be essential in iron homeostasis based on the phenotypes of iron-refractory iron deficiency anemia identified in mouse models as well as in human patients with TMPRSS6 mutations." (PMID 24966834, 2014). "Tmprss6-/-Tfr2-/- double knock out animals develop iron deficiency with high hepcidin, a phenotype similar to Tmprss6-/- mice and to Tmprss6-/-Hfe-/- animals." (PMID 24847265, 2014). "The Tmprss6-/- mice, which have a deletion of the hepcidin inhibitor, the serine protease Tmprss6, is a well established model of iron deficiency anemia with high hepcidin." (PMID 24847265, 2014). "Genetic inactivation of Tmprss6 both in mice and human causes severe, atypical iron deficiency, characterized by microcytic anemia and inability to respond to oral iron treatment, because of inappropriately high hepcidin levels." (PMID 23922777, 2013). "We have previously shown that mice with iron deficiency anemia (IDA)-low hepcidin show a pro-inflammatory response that is blunted in iron deficient-high hepcidin Tmprss6 KO mice." (PMID 23922777, 2013). "In contrast, Tmprss6-/- mice with an inappropriately high hepcidin expression and iron deficiency have increased BMP signaling but decreased Bmp6 expression in the liver." (PMID 23565256, 2013).
iron deficiency (continued). "Our approach of comparing Tmprss6 KO mice with IDA animals eliminates the contribution of iron deficiency to the modulation of gene expression." (PMID 23922777, 2013). "On the contrary, Tmprss6 KO mice, characterized by iron deficient anemia and high hepcidin, have a blunted inflammatory response compared to mice with a diet-induced iron deficient anemia and low hepcidin." (PMID 23922777, 2013). "We found a novel SNP in TMPRSS6 that was associated with serum iron in whites and replicated in African Americans, suggesting a role for this SNP in increasing the risk of iron deficiency in affected persons." (PMID 22761678, 2012). "Rare loss-of-function mutations in TMPRSS6 cause iron-refractory iron deficiency anemia (IRIDA) by upregulating hepcidin due to the inability to cleave hemojuvelin, whereas common TMPRSS6 polymorphisms are a risk factor for iron-deficiency anemia." (PMID 23144979, 2012). "Although mutations in TMPRSS6 are described to be linked to severe iron deficiency anaemia in patients with relatively increased hepcidin levels, we decided to sequence the exons and exon–intron boundaries of the TMPRSS6 gene." (PMID 22509377, 2012). "Mutations in TMPRSS6 cause inappropriately high hepcidin synthesis, resulting in iron-refractory iron deficiency anemia in humans." (PMID 22629388, 2012). "Individuals with loss-of-function mutations in the TMPRSS6 gene show increased circulating hepcidin and iron-refractory iron-deficiency anemia, suggesting that blocking TMPRSS6 may be a viable strategy to elevate hepcidin levels in β-thalassemia." (PMID 40548380, 2025). "Genetic factors, notably variations in the TMPRSS6 gene, are implicated in iron deficiency anemia, yet the precise relationship with anemia remains unclear." (PMID 40081160, 2025). "Additionally, TMPRSS6 polymorphisms in iron deficiency anaemia are partially responsive to oral iron treatment." (PMID 36604716, 2023). "TMPRSS6 is essential for normal systemic iron homeostasis in humans and mutations in TMPRSS6 may cause iron-refractory iron deficiency anemia." (PMID 36782330, 2023). "Similarly, TMPRSS6 deficiency in mice causes microcytic anemia and iron deficiency–related hair loss." (PMID 36986429, 2023). "A study carried out on the TMPRSS6 rs855791 polymorphism in the Egyptian population in 2018 showed a significant increase in frequency of mutations (TT and TC) in the counterpart disease of iron deficiency anemia patients compared to the normal group 20." (PMID 37006987, 2023). "Notably, mutations preventing Tmprss6 activity lead to a rare inherited form of iron deficiency anemia called Iron-Refractory Iron Deficiency Anemia (IRIDA;)." (PMID 37566034, 2023). "Patients with mutations in TMPRSS6 develop iron-refractory iron deficiency anemia." (PMID 36986429, 2023). "During iron deficiency, TMPRSS6 is stabilized on the cell surface and cleaves HJV." (PMID 36986429, 2023). "The variants of TMPRSS6 contribute to the development of iron deficiencies." (PMID 36295822, 2022). "As reported, TMPRSS6 genotype influences iron metabolism, and the mutations in TMPRSS6 may lead to iron deficiency." (PMID 35811975, 2022). "Consistently, young mice with deficiency of TMPRSS6 (coding for matriptase‐2, a liver transmembrane serine protease) causes a hair loss and an iron deficiency anaemia phenotype, characterised by upregulation of hepcidin and blocking iron export into plasma from intestinal." (PMID 35538889, 2022). "Additionally, the authors suggested the potential contribution of the TMPRSS6 rs855791 variant in predicting responses to oral iron supplementation in celiac disease patients affected by iron deficiency anemia." (PMID 36295058, 2022). "Therefore, we sought to develop a tool to assist clinicians in recognizing and differentiating TMPRSS6-related IRIDA from other common causes of iron deficiency anemia (IDA) to ensure timely diagnosis and prevent unnecessary invasive diagnostic workup." (PMID 35163840, 2022).
iron deficiency (continued). "Conversely, TMPRSS6 loss of function may result in unregulated hepcidin synthesis, reduced iron absorption, and iron-deficiency anemia." (PMID 34444942, 2021). "HFE mutations showed a protective role against iron deficiency anemia, while the presence of the TMPRSS6 variant could help to predict oral iron response in anemic patients." (PMID 32349426, 2020). "Although IRIDA is quite rare, it may be at the extreme end of a broad continuum of disease, since TMPRSS6 genetic variants can lead to different degrees of iron deficiency and anaemia." (PMID 32609760, 2020). "Some patients with a phenotype of refractory iron deficiency have been reported to have a single TMPRSS6 mutated allele; here, the debate is whether they should be considered IRIDA or not." (PMID 31649559, 2019). "Interestingly, several TMPRSS6 SNPs have been shown to provide susceptibility to iron deficiency in some populations and in blood donors." (PMID 31649559, 2019). "In addition, to evaluate the specific contribution of the hypoferremic phenotype of Tmprss6−/− mice in the outcome of the experiment, we treated Tmprss6−/− mice with intraperitoneal injections of iron-dextran to revert their plasma iron deficiency." (PMID 29636509, 2018). "The high expression of Hamp in Tmprss6-mutated mice decreases ferroportin protein content at the enterocyte basolateral membrane, resulting in decreased absorption of iron from the diet, depletion of iron stores and iron deficiency anemia." (PMID 29073189, 2017). "Tmprss6-mutated mask mice display iron deficiency anemia and high expression of hepcidin." (PMID 29073189, 2017). "In conditions of iron deficiency, increased TMPRSS6 protein content could thus result in decreased activity of the BMP6/HFE2 signaling pathway, contributing to the well-documented decrease of Hamp expression." (PMID 26845567, 2016). "It was found that TMPRSS6 SNPs was associated with lowered serum iron, hemoglobin, and plasma ferritin levels, consistent with lowered risk of iron overload and increased risk of iron deficiency anemia in Chinese population." (PMID 24966834, 2014). "In order to avoid the confounding effect of acute inflammation and severe iron deficiency, we analyzed whether the TMPRSS6 A736V polymorphism influenced iron parameters and erythropoiesis in patients with CRP < 1 mg/dl and ferritin > 30 ng/ml." (PMID 23433094, 2013). "Rare loss-of-function germline mutations of TMPRSS6 cause iron-refractory iron-deficiency anemia related to extremely high hepcidin levels, whereas the common rs855791 polymorphisms resulting in the p.A736V substitution is a major determinant of iron status in healthy subjects." (PMID 23433094, 2013). "The TMPRSS6 V736A variant was found associated with iron-deficiency anemia." (PMID 23750121, 2013). "Furthermore, mutations in the TMPRSS6 gene have been implicated in iron deficiency anemia refractory to oral iron therapy within white populations." (PMID 22761678, 2012). "Given the wealth of publications describing mutations in two genes (SLC11A2 and TMPRSS6) being associated with iron deficiency anaemia, we initially hypothesized that mutations in these two candidate genes were the reason for this anaemia." (PMID 22509377, 2012). "Genetic alterations in the gene coding for transferrin (TF), transmembrane serine protease 6 (TMPRSS6), and solute carrier family 40 member 1 (SLC40A1) are the primary sources of genetic diversity leading to iron deficiency." (PMID 40081160, 2025). "Two studies analyzed TMPRSS6 and HFE variants in adult and pediatric celiac disease in which, as in IBD, iron deficiency anemia is a very common condition." (PMID 36295058, 2022). "The purpose of the current study is to investigate TMPRSS6 rs1421312 and BMP2 rs235756 SNPs and their association with iron deficiency status among female students at the University of Tabuk, Saudi Arabia." (PMID 34780475, 2021).